CD4 (CD4 molecule)
Diseases named in the same sentence as CD4 in open-access papers (continued):
Sharing a sentence is not in itself a finding about the gene and the disease.
tumor (continued). "It has been demonstrated that human TLR8 signaling can reverse the suppressive functions of naturally occurring Treg cells and tumor-derived CD4+, CD8+, and γδ Treg cells, which resulted in enhanced anti-tumor immunity." (PMID 33102225, 2020). "And we conducted the abundance of six types of tumour‐infiltrating immune cells (B cells, CD4 + T cells, CD8 + T cells, neutrophils, macrophages and dendritic cells) and purity." (PMID 32696617, 2020). "Our data are consistent with previous results, which also describe an increased CD4+ T cell population in the orthotopic tumor." (PMID 33383676, 2020). "While T-bet ablation restricted interferon-γ (IFN-γ) production, loss of Blimp-1 prevented GzmB expression in response to IL-2, suggesting two independent programs required for polyfunctionality of tumor-reactive CD4+ T cells." (PMID 31924474, 2020). "Recently, it has been found that the gut microbiota can promote memory CD4+ T cell formation in tumor-bearing mice and cancer patients." (PMID 32221812, 2020). "A recent study described dramatically suppressed tumor growth upon IDO1 knockdown by increasing the number of CD4+ and CD8+ T cells in murine GBM models." (PMID 32117235, 2020). "Abelin and co-authors suggested that, within tumour microenvironment (TME), CD4+ Th cells are mainly activated by resident APCs, which present neoantigens, derived from endocytosed tumour proteins, in the context of MHC II." (PMID 32183246, 2020). "There was also an increased infiltration of CD4+ T cells that correlated with tumor reduction that is consistent with a supportive or “helper” role of CD4+ T cell to CD8+ T cells against both tumor and viral antigens." (PMID 32198420, 2020). "Acting as an immunosuppressive cytokine, it causes polarization of macrophages to phenotype M2 and recruits naïve CD4+ T cells into the tumor niche via its receptor PITPNM3, which then differentiate into Treg cells responsible for tumor immune evasion." (PMID 33076281, 2020). "Last, the correcting of dysfunctional CD4 T cell by hyperthermia has also been proven by that patients with tumor treated with hyperthermia showed increases in Th17 cells and decreases in Tregs in the peripheral blood." (PMID 33240283, 2020). "Inhibition of MGAT5 reduces tumor growth, enhances the anti-tumor responses by CD4+ T cells and macrophages, and promotes Th1 differentiation." (PMID 32849657, 2020). "The pro- or anti-tumor functions of CD4+ T lymphocytes largely depend on their polarization towards CD4+ T helper (Th1, Th2, Th17) or CD4+ regulatory T cells (Treg)." (PMID 33371274, 2020). "IL-9 knockout mice exhibit strong tumor cell growth inhibition and have more normal activated CD4+ and CD8+ T-lymphocyte production than control mice." (PMID 32228589, 2020). "Treatment significantly increased the infiltration of CD3+ T cells into the liver and tumor and altered the phenotypical composition of infiltrating CD4+ and CD8+ T cells, and DNTs." (PMID 32448803, 2020). "In this study, a mathematical model is proposed for active immunotherapy that includes the effects of natural killer cells, circulating lymphocytes, CD8+T cells, CD4+T cells, and chemotherapy on the tumor." (PMID 32148558, 2020). "In an HPV-associated mouse tumor model, IL-33 promoted IFN-γ and TNF-α production by antigen-specific CD4+ T cells." (PMID 33329534, 2020). "Early mechanistic studies also demonstrated that CD40 stimulation can enhance the efficacy of tumor antigen vaccination, induce activation of endogenous CD4+ T cells and reverse cytotoxic T cell tolerance." (PMID 33101304, 2020). "Lower level of resting mast cells and resting CD4 memory T cells as well as higher levels of the activated counterparts characterize the tumor microenvironment in ever-smokers." (PMID 32646072, 2020). "The dominant Cyp11a1+ tumor-infiltrating immune cells were identified as T cells, predominantly CD4+ (helper T cells)." (PMID 32680985, 2020).
tumor (continued). "These cells—similar to CD4+ T cells—have effector functions that can either support or suppress anti-tumor immunity." (PMID 33324425, 2020). "Flow cytometry analysis of tumors harvested after seven consecutive treatments showed that CEA-TCB treatment induced >10-fold increase in intra-tumor T-cells and >3-fold increase in the intra-tumor CD8/CD4 T-cell ratio." (PMID 33330050, 2020). "Overexpression of EBV miR-BART1-5p in EBV-associated tumor cells can inhibit the expression of LY75, and promote tumor cells to get rid of the recognition and monitoring of CD4+ Th cells and CD80+ CTL cells." (PMID 32127936, 2020). "These polyfunctional CD4+ T cells exhibit potent anti-tumor activity in an adoptive transfer setting with therapeutic implications." (PMID 31924474, 2020). "In a mouse model of HCC, both TGF-β and IL-10 have been found to be associated with tumor progression, and in vitro TGF-β has been found to promote the differentiation of Foxp3+CD4+ Tregs." (PMID 32488850, 2020). "The effector function of tumor-infiltrated CD4+ T cells is readily suppressed by many types of immune regulators in the tumor microenvironment, which is one of the major mechanisms of immune tolerance against cancer." (PMID 32604872, 2020). "The interaction of tumor-antigen presenting dendritic cells and CD4+ T helper cells releases chemokine CCL3 and CCL4 that in turn attract CCR5+ cytotoxic CD8+ T cells." (PMID 33414786, 2020). "We also confirmed that the tumor size (P=0.096), tumor capsule (P=0.083) and CD4/CD8 expression (P=0.107) have the trend with HCC survival." (PMID 32742491, 2020). "The predominant tumor infiltrating lymphocytes are CD4+ T helper cells, CD8+ cytotoxic T cells, and regulatory T cells." (PMID 33344239, 2020). "CD8 T cells that directly target tumor cells are robust, however, CD4 T cells in the tumor microenvironment are ambiguous for a wide range of subsets with potentially different functions." (PMID 31988638, 2020). "Pro-inflammatory (M1) macrophages promote cytotoxic and anti-tumor CD8 and CD4 responses, whereas anti-inflammatory M2 macrophages contribute to Th2 responses, tissues repair and tumor growth." (PMID 32391124, 2020). "When relapsed tumor tissue was analyzed to assess post-vaccination changes, increased CD4+ and CD8+ T cell infiltration was observed in dexamethasone-untreated patients, but not in dexamethasone-treated patients." (PMID 32245497, 2020). "In contrast, we found that the frequency of Ki-67+CD4+ T cells was highest in the bulk tumor (center panel)." (PMID 32763154, 2020). "Glucose deprivation also suppresses anti-tumor effector functions of intratumoral Th1 CD4+ T cells by limiting the Ca2+-NF-AT1 signaling pathway in CD4+ T cells." (PMID 32775303, 2020). "MDSCs are a heterogeneous population of immature myeloid cells that are recruited to the primary tumor as well as metastatic sites and play a crucial role in inhibiting innate and adaptive immune responses by suppressing CD4 T-cells, CD8 T-cells, and NK cells." (PMID 31811337, 2020). "Programmed death ligand 1 (PD‐L1) blockade upregulated specific tumor‐infiltrating CD4+ and CD8+ T‐cell subsets." (PMID 33135337, 2020). "We therefore evaluated the potential contribution of Cγ receptor cytokines to the gain of GzmB in tumor-reactive CD4+ T cells." (PMID 31924474, 2020). "Meanwhile, activated CD4+ memory T lymphocytes and CD4+ helper T cells can target antigenic tumor cells, inhibit tumor growth, and have a positive regulatory role in anti-tumor immunity." (PMID 33584797, 2020). "In contrast, a clinical study with NSCLC patients revealed that the accumulation of CD4+ FOXP3- PD-1 high T cells within the tumor and peripheral blood correlated with higher tumor burden." (PMID 33329566, 2020). "In the tumor microenvironment, the main lymphocyte populations include either CD4 or CD8 positive cells." (PMID 32850361, 2020).
tumor (continued). "The immunosuppressive and pro-tumorigenic contribution of regulatory CD4+ T cells in the tumor microenvironment is well established." (PMID 32085796, 2020). "It has been suggested that injections of DEXs harbouring MHC/tumour peptide complexes would mediate tumour growth retardation with MHC-restricted antigens presenting CD4+ and CD8+ T cell responses." (PMID 32276342, 2020). "For example, a single i.t. injection of IL-12-loaded microspheres with and without GM-CSF-loaded microspheres induced apoptosis and elimination of tumor-infiltrating CD4+CD25+Foxp3+ T suppressor cells." (PMID 33178203, 2020). "In certain cancers, CD4+FOXP3+ T cells in tumor tissue were classified into two functional subtypes by the level of FOXP3 expression." (PMID 32377339, 2020). "In another study,both conventional and CD4+CD25-FOXP3+ Tregs weredetected in tumor draining lymph nodes of colorectalcancer patients but CD25- T cells were characterizedwith lower suppressive properties." (PMID 31721539, 2020). "Mice treated with G100 also had significantly higher levels of tumor antigen-specific CD4 and CD8 T cells that secrete IFNγ and IL2 after in vitro stimulation with A20 cells." (PMID 32974162, 2020). "The correlation coefficients between USP1 expression and the abundances of six immune infiltrates (B cells, CD8 + T cells, CD4 + T cells, macrophages, neutrophils and dendritic cells) were analysed using Spearman tests (tumour purity adjusted)." (PMID 32951278, 2020). "At a later stage of tumor development, when CD4+ Treg cells dominate the tumor-microenvironment, CD4+ Tregs mediate the clonal deletion of these tumor-suppressive KIR+ IFNγ+ CD25+ CD8+ T cells and ensure tumor immune evasion." (PMID 33076479, 2020). "CD3, CD4, CD8, HLA-I, HLA-DR tumor cells staining were associated with a “low inflammatory profile” subset." (PMID 32646072, 2020). "There are abundant mechanisms in which cancer cells can escape immune recognition including downregulating MHC Class I and promoting immune suppressive CD4+ T regulatory cells/MDSCs within the tumor microenvironment." (PMID 32911646, 2020). "These approaches have mostly targeted tumor-reactive CD8+ T cells, but in view of the important role and efficacy of tumor-reactive CD4+ T cells strategies to rapidly isolate that specific T cell fraction are needed." (PMID 33425717, 2020). "In the current study, the same tumor has been abolished with a lower dose of chemotherapy combined with CD4+T cell therapy." (PMID 32148558, 2020). "Tumor evoked B regulatory cells (tBregs) play a primary role in lung metastases by the conversion of resting anti-tumor CD4+ T cells into FoxP3+ expressing Treg cells through the paracrine action of TGFβ and CCL22 expressed from lung." (PMID 33414786, 2020). "Percent of IFN-γ/IL-2 secreting CD4+ T cells specific to this autoepitope positively correlated with the tumor size." (PMID 32570805, 2020). "Intriguingly, we detected PD‐1 expression on both CD8 and CD4 T cells in the tumor stroma, including infiltration of the epithelial tumor compartment by CD8+PD1+ cells." (PMID 32615027, 2020). "Thereafter, cell hypoergy and the selection of an hTERT-independent viable CD4+ subset of tumor cells were proposed." (PMID 32992463, 2020). "Effector CD4+, resting Treg, and suppressive Treg cells are transcriptionally different; Tumor‐infiltrating Treg cells have many activation‐induced changes including upregulated expression of chemokines, chemokine receptors, cytokines, and interleukins." (PMID 32659053, 2020). "In contrast, depletion of CD4 T cells or NK cells had minimal effect on G100–ZVex-mediated anti-tumor efficacy, showing that CD8 T cells are the main effectors induced by the combination therapy." (PMID 32579133, 2020). "TIMER analysis revealed that KLRB1, SIT1, and GZMM were negatively correlated with tumor purity and positively correlated with the infiltration of B cells, neutrophils, macrophages, CD4 T cells, CD8 T cells, and dendritic cells." (PMID 33164640, 2020).
tumor (continued). "Further characterization of these cells showed that the increased IL-22 frequency in the tumor was owing to an enrichment of IL-17A+IL-22+ double producing CD4+ T cells, whereas IL-17A-L-22+ single producing T cells were not changed." (PMID 32451418, 2020). "Interleukin-1β activates innate immune cells including antigen presenting cells, and drives polarization of CD4+ T cells towards T helper type (Th) 1 and Th17 cells, to exert anti-tumor effects." (PMID 33322487, 2020). "Patient #1, #2, #3 and #4 showed CD4 anti-tumor reactivity, with respectively 21.1%, 8.2%, 2.3% and 3.8% positive cells, against TD." (PMID 32547707, 2020). "T cells (CD8+ T cells and CD4+ T cells) are the key immune cells that kill tumor cells by activating the immune system." (PMID 33072579, 2020). "In the present study, we analyzed T-cell properties in TET tissues from the aspect of anti-tumor immunotherapy, with a specific focus on CD4 and CD8 single-positive T cells." (PMID 32132638, 2020). "We used IHC to examine changes in CD3+ and CD4+ lymphocytes within the tumor tissues due to captopril treatment." (PMID 32448803, 2020). "In this extended version of the model, four populations of cells are considered: tumor cells, dendritic cells, CD4+ and CD8+ T cells." (PMID 33281620, 2020). "Using unsupervised cluster analysis, we identified eight T cell types from tumor tissue, including tumor-Treg, CD4+/CD8+TRM T cell, CD4+/CD8+ effector memory T cells, Th17 cells, CD8+ exhausted T cells, and CD8+ intraepithelial lymphocytes." (PMID 33584715, 2020). "This is underpinned by the observation that clinical treatment regimens aiming for induction of tumor-specific helper CD4+ T cells led to durable anti-cancer responses." (PMID 32674488, 2020). "While CD8+ T cells are major players involved in the anti-tumor response, the additional induction of CD4+ T cells has proven to be beneficial for clinical responses." (PMID 33255564, 2020). "Liver tumor infiltration lymphocytes was dominated by CD8+T cells in the tumor tissues and CD4+T cells were higher than CD8+T cells in peritumoral area." (PMID 32815653, 2020). "In general, CD11b+ DCs are more effective at driving CD4+ helper T cell responses; however, the role of these DCs in tumor immunity remain largely unexplored." (PMID 32132993, 2020). "Taken together, it becomes evident that Tregs are tumor-promoting, whereas the role of the effector CD4+ T cells is debatable." (PMID 32397303, 2020). "We characterized the antitumor response by mapping infiltration of CD4+ and FOXp3+ cells in the tumor microenvironment." (PMID 32469935, 2020). "Specifically, IL-4 and TGF-β have been reported to be indispensable for the cell priming and differentiation of IL-9-producing CD4+ Th9 cells, which are a subset of CD4+ T helper cells with a powerful anti-tumour capacity." (PMID 33114183, 2020). "Intracaecal tumours had a higher frequency of infiltrating CD3+ CD4+ T cells and a lower frequency of CD3-CD19- (putative NK cells) than subcutaneous tumours." (PMID 33292783, 2020). "Collectively, our results suggest that Ocs-P can promote the antitumor effect by generating multifunctional CD4+ and CD8+ T cells based on the restoration of tumor-associated DC maturation." (PMID 33105813, 2020). "Upon antigen uptake, DCs travel to the tumor draining lymph nodes (LNs) where they encounter CD4+ and CD8+ T cells." (PMID 33207601, 2020). "Compared with the PBS-treated mice, significant tumor growth was found in the mice depleted of CD4+ or CD8+ cells." (PMID 32759233, 2020). "CD4+Foxp3+ Tregs represented a large proportion of TILs in claudin-low tumours, and Tregs isolated from tumours were able to suppress effector T cell responses." (PMID 32680511, 2020).
tumor (continued). "Treatment with diphtheria toxin (DT), induces long-lasting depletion of DCs thus permitting the assessment of the direct priming of naïve CD4+ T cells by MHC-II-expressing tumor cells." (PMID 33138029, 2020). "In line with our observation, Feuerer and colleagues also found that the number of memory cells (CD4+/CD8+ CD45RO+) in the bone marrow of patients with BC increased in parallel with tumor cell metastases to the bone marrow." (PMID 32228503, 2020). "CD4+ transfer into lymphodepleted animals or regulatory T (Treg) cell depletion promoted GzmB expression by tumor-infiltrating CD4+, and this was prevented by interleukin-2 (IL-2) neutralization." (PMID 31924474, 2020). "CD4+ helper T cells contribute important functions to the immune response during pathogen infection and tumor formation by recognizing antigenic peptides presented by class II major histocompatibility complexes (MHC-II)." (PMID 32887877, 2020). "Although IFNγ production has been shown to inhibit angiogenesis, these results highlight a mutual positive regulation between CD4+ T cells and tumor vessel normalization." (PMID 33096748, 2020). "Although number of tumor-infiltrating Tregs was comparable among the 3 subtypes, the proportion of tumor-infiltrating Tregs in CD4+ T cells in MCM was significantly higher than in CM and ALM." (PMID 33392063, 2020). "A meta-analysis of 8,600 patients with lung cancer indicated that a high level of CD8+ T cell infiltration in the tumor nest and tumor stroma, and CD4+ T cell infiltration in the tumor stroma showed better survival." (PMID 32944393, 2020). "These anti-CD4 CAR NKs showed 98% tumor regression by day 9, which was much more efficient as compared to unmodified NK treated mice." (PMID 32679920, 2020). "Multiplex immunochemistry was performed to reveal the positive correlation between high LINC02195 expression and an increased number of CD8+ and CD4+ T cells in the tumor microenvironment." (PMID 32435615, 2020). "The lymphocyte fraction showed an increase in CD8 CTL (CD45+ CD3+ CD8+) and CD4 Th cells (CD45+ CD3+ CD4+) in the Cx3cr1‐Rheb1Δ/Δ tumours." (PMID 32567735, 2020). "The CD4+/CD8+ cell ratio was significantly lower in the tumor tissue than in the peripheral blood (p < 0.05)." (PMID 32131750, 2020). "In serous ovarian cancer, inflammatory infiltration with CD8+CD4+FoxP3+ cells, a high degree of tumor vasculature, and overexpression of VEGF were favorable prognostic factors." (PMID 32488850, 2020). "Resemblance with human AITL disease increased upon immune-phenotyping showing that the tumor mouse tissues (spleen, liver, lymph nodes) were marked by a specific increase of CD4+PD1+CXCR5+ICOS+CXCL-13+Bcl-6+ T follicular helper (Tfh) cells as compared to WT." (PMID 32796826, 2020). "Subsequently, we assessed the roles of CD8 T-cells, CD4 T-cells, regulatory T-cells and NK-cells in controlling tumour progression by in vivo depletion." (PMID 32595211, 2020). "In cancer immunotherapy, a major effort has been devoted to the identification of (neo)antigens that drive CD8+ or CD4+ anti-tumor responses." (PMID 32773038, 2020). "In cancer, CD4+FoxP3+ Tregs migrate to tumors to suppress anti-tumor immune responses, allowing cancer cells to persist." (PMID 33375291, 2020). "Infiltration of the tumor microenvironment by CD68+ and CD163+ macrophages, Treg and CD4+ T cells (especially with Th2 phenotype), and high CD4/CD8 ratio is associated to the emergence of resistance to conventional therapy, and a worse prognosis." (PMID 34191173, 2020). "Going on with this patterns, tumor antigens are exposed to lymphocytes which include both the helper (CD4+) and cytotoxic (CD8+) phenotypes which cooperate to each other in order to kill the early transformed cancer cells." (PMID 32213210, 2020). "On the contrary, CD4+ regulatory T cells inhibit anti-tumor immunity and accelerate tumor progression." (PMID 32133292, 2020).